SOCS1 (suppressor of cytokine signaling 1)
Diseases named in the same sentence as SOCS1 in open-access papers (continued):
Sharing a sentence is not in itself a finding about the gene and the disease.
adenocarcinoma (2 papers, 2015 to 2017). A common cancer characterized by the presence of malignant glandular cells. "Tumors at stages II–IV express lower levels of SOCS1 mRNA than those of tumors at stage I; additionally, SOCS1 protein is highly expressed in all of the well-differentiated adenocarcinomas." (PMID 28228755, 2017). "Among the 21 CRC patients with stage II adenocarcinoma, 11 (52%) exhibited above 2-fold increase in SOCS1 expression in tumours, whereas SOCS1 under-expression in tumours was denoted in only 2 (9%) patients." (PMID 26391193, 2015). "Overexpression of SOCS1 in tumour relative to the paired normal mucosa is predominant in stage II adenocarcinomas." (PMID 26391193, 2015). "Likewise, SOCS1 highest relative expression in tumours is prevalent in early-stage I and II adenocarcinomas." (PMID 26391193, 2015). "Stratification of patients according to tumour staging revealed that SOCS1 expression was significantly up-regulated in CRC tumour relative to normal tissues in stage II adenocarcinomas (Wilcoxon matched-pairs signed rank test, P = 0.0216), but not in other stages." (PMID 26391193, 2015). "Moreover, the median tumour-to-normal ratio of SOCS1 expression was significantly elevated in stage II and III adenocarcinomas relative to stage I but not in advanced stage IV (Mann Whitney test)." (PMID 26391193, 2015).
cardiovascular disease (2 papers, 2015 to 2020). "Herein, the effects of PS5, a peptidomimetic of SOCS1, were investigated in a cardiovascular disease model focusing on its antioxidant and atheroprotective properties." (PMID 32824091, 2020). "The inhibition of the main family members—SOCS1 and SOCS3—leads to sustained cytokine activation of STATs and contributes to the progression of inflammatory (including cardiovascular) diseases." (PMID 32824091, 2020).
digestive disease (1 paper, 2023). "In keeping with an important role of these cytokines in P1’s digestive disease and corroborating data in mice showing that negative regulation of IL-12 signaling depends on SOCS1, P1 remission was obtained upon blockade of the P40 subunit common to IL-12 and IL-23 cytokines." (PMID 37156989, 2023).
head and neck tumor (1 paper, 2018). "Importantly, recent studies have reported that resveratrol is a very potent inducer of SOCS1 protein expression in microglia, head and neck tumor cells, and macrophages." (PMID 30213073, 2018).
SOCS1 also shares sentences with these, for which no sentence is quoted: lupus nephritis (6 papers); kidney damage (5); diabetic nephropathy (4); Infectious (4); Parkinson disease (4); acute pancreatitis (3); experimental autoimmune encephalomyelitis (3); metabolic disease (3); myelodysplastic syndrome (3); viral diseases (3); acute lymphoblastic leukemia (2); adenoma (2); allergies (2); bladder cancer (2); Burkitt lymphoma (2); chronic obstructive pulmonary disease (2); chronic periodontitis (2); cutaneous T cell lymphoma (2); esophageal squamous cell carcinoma (2); glomerulonephritis (2); Glucose intolerance (2); idiopathic pulmonary fibrosis (2); listeriosis (2); lymphadenitis (2); myocarditis (2); myopia (2); Primary Sclerosing Cholangitis (2); Salmonella Infections (2); spondylopathy (2); T-cell lymphoma (2).
A further 82 diseases each share a sentence with SOCS1 in 1 paper.